PRR15 (proline rich 15)
Description:
May have a role in proliferation and/or differentiation.
Tractability: No criterion of Open Targets' tractability assessment is met for any kind of drug.
Gene: Protein-coding gene on chromosome 7 (29,563,775 to 29,567,306, forward strand). Ensembl gene ENSG00000176532.
Subcellular location (Human Protein Atlas): Vesicles; Cell Junctions
Gene Ontology:
Molecular function: protein binding
Genetic constraint (gnomAD): Loss-of-function variants: 7 observed, 3.86 expected, observed/expected ratio (o/e) 1.81, 90% interval 0.9 to 1.95. That is too few expected variants to judge how well the gene tolerates losing a copy. Missense variants: 200 observed, 161.68 expected, observed/expected ratio (o/e) 1.24, 90% interval 1.1 to 1.39. Synonymous variants: 82 observed, 66.85 expected, observed/expected ratio (o/e) 1.23, 90% interval 1.02 to 1.47.
Homologues: Orthologues: chimpanzee PRR15 (98% identical), macaque PRR15 (98% identical), dog PRR15 (81% identical), pig PRR15 (79% identical), rabbit PRR15 (74% identical), rat Prr15 (66% identical), mouse Prr15 (65% identical), tropical clawed frog prr15 (45% identical), zebrafish prr15lb (27% identical). Paralogues in human: PRR15L (26% identical).
Diseases named in the same sentence as PRR15 in open-access papers:
PRR15 is named in the same sentence as 29 diseases in open-access papers, as found by Europe PMC text mining. Sharing a sentence is not in itself a finding about the gene and the disease. The quoted sentences say what the papers report.
breast carcinoma (4 papers, 2023 to 2026). "Subsequently, we detected PRR15 mRNA expression using RT-qPCR assay in a panel of mammary epithelial and breast cancer cells to probe the association of PRR15 with breast cancer." (PMID 37072408, 2023). "PRR15 exhibits a complex role in breast cancer, inhibiting epithelial-to-mesenchymal transition while simultaneously activating estrogen receptor signaling, both of which contribute to tumor progression." (PMID 39929816, 2025). "The non-transformed mammary epithelial cell MCF10A showed an intermediate expression of PRR15 than all the other 9 breast cancer cells." (PMID 37072408, 2023). "We determined the loss- and gain-of-function effects of PRR15 on the aggressive ability of breast cancer cells to investigate the biological role of PRR15 in tumor progression." (PMID 37072408, 2023). "The analysis of the transcriptomic data from breast cancer cell lines archived in the CCLE also revealed that PRR15 was significantly less expressed in basal/TNBC cell lines than in luminal cell lines." (PMID 37072408, 2023). "PRR15 expression was elevated in breast cancer, accompanied by reduced gene methylation in tumors." (PMID 39929816, 2025). "The analysis of TCGA data revealed a remarkable association between PRR15 downregulation and higher clinical stages, and the corresponding clinical information of the constructed breast cancer tissue chip also displayed lower PRR15 expression in TNBC patients who experienced metastases." (PMID 37072408, 2023). "In addition, in silico analysis of breast cancer revealed that both PRR15 mRNA and protein expression increases and the gene is hypomethylated in the tumor tissues compared with the healthy counterparts." (PMID 37072408, 2023). "The existing findings on PRR15 and neoplasms remain poorly defined and underexplored, with basic studies mainly related to CRC and NSCLC and limited to bioinformatics in breast cancer." (PMID 37072408, 2023). "PRR15, which was downregulated in siSHMT2 samples, is a negative regulator for the malignant progression and a clinical prognosis predictor of breast cancer by modulating the PI3K/Akt signaling." (PMID 41347062, 2025). "PRR15 knockdown or overexpression was generated in breast cancer cells, including TNBC (MDA-MB-231 and CAL51) and non-TNBC (MCF7 and T47D) cells." (PMID 37072408, 2023). "Specifically, PRR15 expression in breast cancer was positively correlated with CNV of non-TNBC (P = 0.0013), but not with TNBC." (PMID 37072408, 2023). "Furthermore, PRR15 expression was much lower in TNBC cells than in MCF10A and less aggressive/metastatic luminal-like, together with HER2amp breast cancer cells, which was further validated using CCLE panel." (PMID 37072408, 2023). "IHC staining of breast cancer tissue microarray suggested that the percentage and intensity of PRR15-positive cells were lower in TNBC than in non-TNBC." (PMID 37072408, 2023). "Likewise, the analysis of scRNA-seq data from breast cancer supported this finding, with non-TNBC subnets, including luminal A, luminal B, and HER2amp, possessing higher PRR15 expression relative to TNBC." (PMID 37072408, 2023).
colon cancer (4 papers, 2020 to 2025). "Co-expression network analysis has indicated PRR15 is a critical gene during PHY906 and CPT11 combined treatment of colon cancer." (PMID 34316393, 2021).
colorectal cancer (3 papers, 2017 to 2023). A primary or metastatic malignant neoplasm that affects the colon or rectum. "As for lncRNA, AC007255.8 is an antisense transcript of proline rich 15 (PRR15), which is overexpressed in advanced stage human colorectal cancer and its expression was correlated with patient age." (PMID 29351231, 2018).
non-small cell lung carcinoma (3 papers, 2021 to 2025). A group of at least three distinct histological types of lung cancer, including non-small cell squamous cell carcinoma, adenocarcinoma, and large cell carcinoma. "This study investigates the expression, functional significance, and underlying mechanisms of PRR15 in non-small cell lung cancer (NSCLC)." (PMID 39929816, 2025). "Instead, a study presenting opposite conclusions illustrated that the CpG of PRR15 is significantly methylated in bronchial washings from non-small cell lung cancer (NSCLC) patients, leading to its reduced expression." (PMID 37072408, 2023). "Genome-wide analysis of DNA methylation in bronchial lavage fluid has exhibited a distinct PRR15 CpG methylation for patients with non-small cell lung cancer." (PMID 34316393, 2021).
breast invasive carcinoma (2 papers, 2020 to 2023). "A remarkable positive correlation was observed between PRR15 CNV and mRNA expression in 11 tumor types, such as ovarian serous cystadenocarcinoma, breast invasive carcinoma (BRCA), and low-grade glioma (LGG)." (PMID 37072408, 2023).
glioma (2 papers, 2023). A benign or malignant brain and spinal cord tumor that arises from glial cells (astrocytes, oligodendrocytes, ependymal cells). "Our previous published research in brain cancer identified the 5hmC modification level of the PRR15 gene (encoding ‘proline rich 15’), specifically its gene body modification as one of the cfDNA-based diagnostic markers for gliomas." (PMID 37387524, 2023).
lung adenocarcinoma (2 papers, 2023 to 2025). A carcinoma that arises from the lung and is characterized by the presence of malignant glandular epithelial cells. "Single-cell sequencing analysis of lymph node metastatic (mLN) lung adenocarcinoma (LUAD) tissues revealed overexpression of PRR15 specifically within epithelial cell populations." (PMID 39929816, 2025). "Additionally, high PRR15 expression was linked to better OS in thyroid carcinoma but worse OS in LGG, lung adenocarcinoma, and pancreatic carcinoma." (PMID 37072408, 2023). "Analysis of TCGA (The Cancer Genome Atlas) data in NSCLC revealed significantly elevated PRR15 levels in NSCLC [lung adenocarcinoma (LUAD) + squamous cell carcinoma (LUSC)] tumor tissues compared to normal lung parenchyma, suggesting a potential role for PRR15 in NSCLC pathogenesis." (PMID 39929816, 2025).
triple-negative breast carcinoma (2 papers, 2023 to 2025). An invasive breast carcinoma which is negative for expression of estrogen receptor (ER), progesterone receptor (PR), and human epidermal growth factor receptor 2 (HER2). "An earlier study demonstrated that PRR15 inhibited Akt-mTOR activation in triple-negative breast cancer (TNBC) cells, suggesting a context-dependent role for this protein." (PMID 39929816, 2025).
gastric cancer (1 paper, 2023). A primary or metastatic malignant neoplasm involving the stomach. "PRR15 expression also varied in a series of cell lines from CCLE dataset, with the top three being colorectal, pancreatic, and gastric cancer cell lines." (PMID 37072408, 2023).
lentivirus infection (1 paper, 2017). Virus diseases caused by the Lentivirus genus. "Lentivirus infection led to a 68% decrease in PRR15 mRNA (p<0.01) as measured by qPCR, with a 62% reduction (p<0.06) in the microarray analysis." (PMID 28380025, 2017).
myeloma (1 paper, 2023). "According to the Oncomine program, PRR15 expression was high in breast, esophageal, head and neck, myeloma, and pancreatic cancers." (PMID 37072408, 2023).
Pleural effusion (1 paper, 2025). The presence of an excessive amount of fluid in the pleural cavity. "Furthermore, analysis of LUAD pleural effusion (PE) samples confirmed the pronounced expression of PRR15 within epithelial cell populations." (PMID 39929816, 2025).
prostate adenocarcinoma (1 paper, 2023). "PRR15 methylation profiles in pan-cancer were explored, revealing that PRR15 methylation degrees were markedly reduced in several tumors than in normal tissues, including BRCA, uterine corpus endometrial carcinoma, and prostate adenocarcinoma." (PMID 37072408, 2023).
testicular germ cell tumor (1 paper, 2023). A germ cell tumor arising from the testis. "PRR15 methylation was negatively linked to mRNA expression in 16 tumors, including BRCA, but it exhibited a positive relationship in testicular germ cell tumor." (PMID 37072408, 2023).
tumor (6 papers, 2017 to 2025). "In vivo studies further validated these findings, demonstrating that PRR15 knockdown suppressed tumor growth in xenograft models." (PMID 39929816, 2025). "Fluorescence staining assays in tumor slides revealed a higher percentage of TUNEL-positive nuclei in PRR15-silenced tumors, further supporting apoptosis induction." (PMID 39929816, 2025). "Single-cell RNA sequencing confirmed PRR15 overexpression within the malignant tumor cell population." (PMID 39929816, 2025). "In vivo studies using xenograft models further validated the oncogenic role of PRR15, demonstrating that PRR15 knockdown suppressed tumor growth and attenuated Akt-mTOR activation." (PMID 39929816, 2025). "Tumor tissues with substantially decreased PRR15 expression also revealed a significantly increased p-PI3K and p-Akt expression, providing evidence on the oncogenic role of PRR15 low expression mediated by the PI3K/Akt signaling pathway." (PMID 37072408, 2023). "Proline rich 15 (PRR15) is a protein involved in the progression of several tumor types, but its mechanisms are still controversial." (PMID 37072408, 2023). "The research available on PRR15 is scarce, focusing on embryonic development, neurological diseases, and several tumor studies." (PMID 37072408, 2023). "TNFSF10, also known as TRAIL, is a death receptor ligand known to induce apoptosis in transformed and tumor cells; TFNSF10 was up-regulated in PRR15-deficient cells (8.1-fold, p = 0.011)." (PMID 28380025, 2017). "Additionally, the assessment of PRR15 protein expression showed an increase in tumor tissues from four representative patients (referred to as “T1” to “T7”)." (PMID 39929816, 2025). "Afterwards, we depicted the copy number variation (CNV) landscape of PRR15 in various neoplasms." (PMID 37072408, 2023). "The role of PRR15 in tumor progression is still controversial." (PMID 37072408, 2023). "We further verified the expression levels of ADAMTS9, ENTPD1, FRMD3, PRR15, AKAP12 in THCA, and the results of GEPIA database showed that ENTPD1, FRMD3, PRR15 were obviously increased in tumor tissues (n=512) compared with normal tissues (n=337), and the difference was statistically significant." (PMID 35756646, 2022). "Thus, PRR15 silencing demonstrably compromised Akt-mTOR signaling, resulting in consequent suppression of proliferation, induction of apoptosis, and ultimately, impeded NSCLC xenograft tumor growth." (PMID 39929816, 2025). "Moreover, PRR15 silencing allowed the growth of transplanted tumors formed by CAL51 cells, consistent with previous findings of statistically significant differences in tumor volume and weight, as well as mouse body weight between the two groups." (PMID 37072408, 2023). "In contrast, PRR15 knockdown did not exacerbate the initiation and progression of non-TNBC MCF7 cells in NOG mice, and no marked differences were observed between PRR15-silenced xenografts and controls in terms of tumor volume, tumor weight, and mouse body weight." (PMID 37072408, 2023).
cancer (5 papers, 2021 to 2025). A tumor composed of atypical neoplastic, often pleomorphic cells that invade other tissues. "We then found that the most significant DEGs were tightly associated with progression of cancers, including PTMA, HNRNPR, RAPH1, TRAF3IP1, CNBP, and PRR15." (PMID 41347062, 2025). "The findings detailed above convincingly illustrated the significant anti-cancer effects resulting from the silencing or KO of PRR15 in both primary and immortalized NSCLC cells." (PMID 39929816, 2025). "Pan-cancer analysis was performed since the studies available on the role of PRR15 in tumors are scarce." (PMID 37072408, 2023). "The silencing of PRR15 enhanced cancer initiation and progression by regulating the PI3K/Akt signaling in vitro and in vivo." (PMID 37072408, 2023). "Overall survival analysis and gene expression correlations for AC007255.1 and PRR15 across 33 kinds of cancers from TCGA database." (PMID 34316393, 2021). "It is important to note that there are limited studies examining the role of PRR15 in cancer." (PMID 39929816, 2025). "Thus, multiple lines of evidence derived from single-cell sequencing and pleural fluid analyses consistently demonstrate overexpression of PRR15 within cancer cell populations of metastatic LUAD." (PMID 39929816, 2025). "Subsequent analysis of PRR15 expression demonstrated significant PRR15 overexpression in cancer cell populations compared to non-malignant cells, with particularly elevated levels observed in both LUAD and LUSC subtypes." (PMID 39929816, 2025). "Moreover, in most kinds of cancers, AC007255.1 expression was significantly correlated to PRR15 expression." (PMID 34316393, 2021).
GI tumors (2 papers, 2023 to 2025). "In mouse GI tumors, increased PRR15 expression was linked to mutations in the AP (adenomatous polyposis coli) gene, similar to findings in human CRC." (PMID 39929816, 2025). "Research on PRR15 expression in gastrointestinal (GI) cancers revealed varying levels in mouse GI tumors and human colorectal cancer (CRC) as a result of diverse gene mutations." (PMID 39929816, 2025).
infection (1 paper, 2017). The state of being infected such as from the introduction of a foreign agent such as serum, vaccine, antigenic substance or organism. "Transfection and infection of ACH-3P cells with a shRNA to target PRR15 mRNA for degradation resulted in a comparable decrease in PRR15 mRNA concentrations for both methods." (PMID 28380025, 2017).
PRR15 also shares sentences with these, for which no sentence is quoted: brain cancer (1 paper); breast tumor (1); colon adenocarcinoma (1); lung carcinoma (1); neurological disorders (1); ovarian serous cystadenocarcinoma (1); pancreatic carcinoma (1); Papillary Thyroid Cancer (1); squamous cell carcinoma (1); thyroid carcinoma (1); uterine corpus endometrial carcinoma (1).